CD34 (CD34 molecule)
Diseases named in the same sentence as CD34 in open-access papers (continued):
Sharing a sentence is not in itself a finding about the gene and the disease.
non-Hodgkin lymphoma (14 papers, 2012 to 2026). Distinct from Hodgkin lymphoma both morphologically and biologically, non-Hodgkin lymphoma (NHL) is characterized by the absence of Reed-Sternberg cells, can occur at any age, and usually presents as a localized or generalized lymphadenopathy associated with fever and weight loss. "Studies have shown that a higher CD34+ cell dose was associated with improved PFS and OS after auto-HCT in non-Hodgkin lymphoma and Hodgkin disease." (PMID 39482325, 2024). "The first clinical study that applied the lentiviral vector for anti-HIV gene delivery introduced a triple combination of a Tat/Rev shRNA, a TAR decoy, and a CCR5 ribozyme into CD34+ cells of patients with AIDS-related non-Hodgkin lymphoma (NHL)." (PMID 35216446, 2022). "Lymphoblastic lymphoma is an aggressive non-Hodgkin lymphoma composed of lymphoblasts and an immature phenotype with expression of TdT and/or CD34." (PMID 26416427, 2015). "Nevertheless, other studies reported that plerixafor (either with G-CSF alone or in association with chemotherapy) elicits a lower rate of collection of sufficient transplant doses and lower CD34+ cell yield in patients with non-Hodgkin lymphoma compared to patients with either MM or HL." (PMID 36675546, 2023). "Plerixafor in combination with G-CSF has shown to significantly increase the number of peripheral CD34 + cells as compared to G-CSF alone when used upfront in multiple myeloma (MM), non-Hodgkin lymphoma (NHL), and Hodgkin lymphoma (HL) patients undergoing ASCT." (PMID 38994380, 2022).
autoimmune disease (13 papers, 2011 to 2025). A disorder resulting from loss of function or tissue destruction of an organ or multiple organs, arising from humoral or cellular immune responses of the individual to their own tissue constituents. "Collectively, the study data indicate that a decrease in CD34+ cells in glomerular capillaries correlates with the progression of GLs in autoimmune disease-prone Yaa mice." (PMID 28870174, 2017). "Another methodic question is whether to use CD34+ selection in autologous HSCT for autoimmune diseases." (PMID 36359859, 2022). "Furthermore, we now dissect the origin of human T cells from the neonatal thymus tissue vs the injected CB CD34+ cells and address the development of autoimmune disease in this model as well as the ability of neonatal thymic tissues of different ages to support human T cell reconstitution." (PMID 37251390, 2023). "We recently demonstrated that human T cells play a requisite role in inducing a multiorgan autoimmune disease that develops in HIS mice that have a native murine or grafted human thymus and receive human CD34+ cells intravenously." (PMID 40293219, 2025). "Expansion of the immature transitional CD10+CD34- B cell population is observed during acute clinical P. falciparum malaria, HIV infection and in autoimmune diseases." (PMID 22166136, 2011). "In CD, nearly half of studies used CD34+ selection, although a clear benefit has not been demonstrated yet in autoimmune diseases, and EBMT guidelines suggest against routine usage of selection outside of experimental settings." (PMID 36359859, 2022). "Although there is no consensus and still a matter of debate in transplantation for other autoimmune diseases, CD34+ selection has not been investigated in T1D." (PMID 29868031, 2018).
brain tumors (13 papers, 2005 to 2025). "Recently, the molecular markers of CD34 and BRAF mutation were interestingly found to be associated with brain tumors with epilepsy, especially GNT3–7." (PMID 36307486, 2022). "PXAs are semi-benign brain tumors that share molecular and morphological commonalities with traditional LEATs, such as CD34 immunoreactivity in 73% of cases of PXAs and BRAFV600E mutation in 50–75% of analyzed PXAs." (PMID 36699536, 2022). "Multipotent progenitors (MPPs), defined by the expression of Lin-CD34+CD38-CD45RA-CD90- were also overrepresented in brain tumor tissues compared to the healthy bone marrow sample." (PMID 34162860, 2021). "Brain tumors from both control and FMOD-depleted variant cells showed similar staining for the proliferation marker Ki67 and TUNEL reaction for apoptosis, as well as for the endothelial cell-specific marker CD34." (PMID 35737114, 2022). "Results showed that H1-Vastatin significantly reduced CD34+ cells in brain tumours." (PMID 28193190, 2017). "One qRT-PCR from the Netherlands utilized CD34+ progenitor cells from two children with brain tumor as controls, and one another study used cancer-free children with fractures as controls, although it is unclear whether these practices could interfere with measured outcomes." (PMID 36010971, 2022). "Brain tumors derived from either SOX2-depleted or control cells showed similar Ki67, TUNEL and CD34 staining." (PMID 35737114, 2022).
breast tumors (13 papers, 2015 to 2025). "We first determined that GPER is co-expressed with IGF1R and with the vessel marker CD34 in human breast tumors (n = 4972)." (PMID 29212519, 2017). "To validate this important role of NCOA1, we performed semi-quantitative immunohistochemistry (IHC) for NCOA1 in the tumor cells and CD34 in the vascular endothelial cells of small blood vessels in 140 human breast tumors." (PMID 26287601, 2015). "CDK11p58 inhibited the expression of VEGF, CD31 and CD34 in breast tumors compared with the control group." (PMID 26470709, 2015). "These large, independent patient datasets, comprising 4972 breast tumors, suggested to us that GPER, IGF1/IGF1R signaling and blood vessel density (CD34) are correlated, and that GPER and IGF signaling may be linked to changes in the breast tumor microenvironment." (PMID 29212519, 2017). "The findings demonstrated that PDOs were able to maintain the expression of CD34, and CD45 subpopulations to recapitulate the cellular heterogeneity of the breast tumors." (PMID 40821783, 2025). "The apparent reduced angiogenic proteins (CD34 and Factor VIII) expressions and down-regulated metastasis-related VEGFR1 and CXCR4 gene expressions were observed in breast tumors." (PMID 27731376, 2016). "Moreover, transcriptional signatures for CD34+ and CD34– CAF clusters were enriched in human normal fibroblasts and breast tumors, respectively." (PMID 40216939, 2025). "Due to the interplay between hypoxia, stemness, and angiogenesis, we examined the degree of vascularization of the 3D stem-like spheroid-derived breast tumor xenografts by immunostaining for CD31 and CD34, reported to be markers of angiogenesis and indicative of a poor prognosis." (PMID 34205080, 2021). "CAFs may also be derived from bone marrow-derived mesenchymal stem cells (BM-MSCs), as PDGFR-α−, CD45−, CD34− BM-MSCs are recruited into primary breast tumors to differentiate into α-SMA+, PDGFR-α−, CD45−, CD34− CAFs." (PMID 34177955, 2021). "Interestingly, in human breast tumor samples, GPER expression correlates with IGF1R and with the vessel marker CD34, corroborating the engagement of GPER and IGF1 system in breast tumor angiogenesis in breast tumor microenvironment." (PMID 29212519, 2017). "In both datasets, a strong, positive correlation in expression was found between GPER and IGF1R, and between GPER and the microvessel density marker CD34, indicating that IGF1R and GPER may be involved in angiocrine regulation of the breast tumor microenvironment." (PMID 29212519, 2017). "Histological and immunohistochemistry tests using p63, SMA, calponin, and Ki67 markers for the breast tumor and DOG-1, CD34, and CD117 markers for the gastric tumor revealed the non-invasive benign state." (PMID 37755162, 2023). "Furthermore, our data regarding the integrated bioinformatic analysis of gene expression studies from human breast tumor samples, evidence that GPER and the IGF1/IGFIR system may be regarded as a peculiar angiocrine signature, for their co-expression pattern with the microvessel-density marker CD34." (PMID 29212519, 2017).
epilepsy (13 papers, 2011 to 2024). A brain disorder characterized by episodes of abnormally increased neuronal discharge resulting in transient episodes of sensory or motor neurological dysfunction, or psychic dysfunction. "The study found that while CD34 expression was significantly associated with a longer duration of epilepsy, BRAF mutation was associated with multiple seizure types." (PMID 36894761, 2023). "In present study, we found GNT with CD34 expression occurred more in adults than children (OR 2.5, P = 0.014), and CD34 expression was also associated with longer duration of epilepsy (P = 0.027) and drug-resistant epilepsy (P = 0.036) by univariate analysis." (PMID 36307486, 2022). "The aim of the study was to evaluate the clinicopathological features, as well as the surgical prognosis, of epilepsy-associated glioneuronal tumors (GNT) with CD34 expression and BRAF mutation." (PMID 36307486, 2022). "The study found that while CD34 expression (59.1% of cases) was significantly associated with a longer duration of epilepsy (median duration of 16 years), BRAF mutation (50% of cases) was associated with multiple seizure types." (PMID 29701169, 2018). "The presence of a prominent CD34-immunoreactive cell element in glioneuronal lesions associated with focal epilepsies points towards an origin from dysplastic and/or neoplastically transformed precursor cells." (PMID 22389832, 2011). "CD34 expression or BRAFV600E mutation in GNT are closely with epilepsy in patients, which may also partly influence the distribution of clinicopathological features of patients." (PMID 36307486, 2022). "Similarly, the lesions we describe as PLNTYs would appear to lie among CD34-expressing neoplasms constituting a subset of growths for which Blumcke and colleagues have proposed the designation “long-term epilepsy associated tumors” (LEATs)." (PMID 27812792, 2017). "Research indicates that CD34-positive tumor cells can trigger an inflammatory response, leading to inflammation and damage to surrounding brain tissue, thereby increasing the risk of epileptic seizures, which clinically manifests as a significant association with a longer history of epilepsy." (PMID 39634774, 2024). "The GG are the most common tumor type in patients with epilepsy and also frequently reported with CD34 expression, ranging from 60 to 90%." (PMID 36910263, 2023). "GNT, as the most common tumor type in patients with epilepsy, are also frequently reported with CD34 expression, approximately 50–60%3,4." (PMID 36307486, 2022). "In our study, we reviewed the CD34 expression in GNT with epilepsy and found 80.2% of tumors were CD34 positive." (PMID 36307486, 2022). "CD34 expression and BRAFV600E mutation are closely associated with GG in patients with epilepsy, which may also partly influence the distribution of clinical and pathological features in patients with GG." (PMID 36910263, 2023). "Thus, we aimed to evaluate the associations of clinicopathological features, as well as surgical prognosis, with molecular expression of CD34 and BRAFV600E mutations in GG with epilepsy." (PMID 36910263, 2023). "Even so, our results could partly complement the undefined domains of the clinicopathological features of molecular alterations (CD34 and BRAF mutation) in GG with epilepsy, as well as the long-term surgical outcomes." (PMID 36910263, 2023). "Thus, we particularly reported our surgical series of GNT further to evaluate the associations of clinicopathological features, as well as surgical prognosis, with molecular expression of CD34 and BRAFV600E mutations in GNT with epilepsy." (PMID 36307486, 2022). "The CD34 expression or BRAFV600E mutation in GG may partly influence the distribution of clinicopathological features of patients with epilepsy, but they may be not able to predict the surgical prognosis of seizure outcome and tumor recurrence." (PMID 36910263, 2023).
epilepsy (continued). "The CD34 expression or BRAFV600E mutation in GNT may partly influence the distribution of clinicopathological features of patients with epilepsy, but they may be not able to predict the surgical prognosis of seizure outcome and tumor recurrence." (PMID 36307486, 2022). "The clinical significance of CD34 expression and BRAF mutation was investigated in a recent publication aiming to study the relationship between biomolecular markers and clinical-pathological features in 22 cases of low-grade epilepsy-associated neuroepithelial tumors." (PMID 29701169, 2018). "Although CD34 expression tends to occur in lesions with epilepsy, the seizure semiology or EEG finding is seldom reported to be related to GG with CD34 expression." (PMID 36910263, 2023). "Although CD34 expression tends to occur in lesions with epilepsy, the seizure semiology or EEG finding is seldom reported to be related to GNT with CD34 expression." (PMID 36307486, 2022). "Second, other factors related to the prognosis of epilepsy-associated tumors were not considered, such as BRAF V600E mutation rate and CD34 positivity rate." (PMID 36672006, 2022). "Immunostaining for CD34 was verified only in the vascular endothelium (no immature CD34-positive cells were observed), irrespective of epilepsy history." (PMID 35002940, 2021). "There were no CD34+ neuroglial cells in any of the surgical epilepsy cases." (PMID 30005693, 2018). "Although the molecular expression of CD34 and BRAFV600E mutation could frequently and exclusively occur in GNT with epilepsy, their clinicopathological features were not yet well defined, as well as the prediction of long-term seizure outcome and tumor recurrence or progression." (PMID 36307486, 2022).
Hodgkins lymphoma (13 papers, 2010 to 2026). A heterogeneous group of malignant lymphoid neoplasms of B-cell origin characterized histologically by the presence of Hodgkin and Reed-Sternberg (HRS) cells in the vast majority of cases. "In contrast, 10 additional patients with Hodgkin lymphoma with higher CD34 dose, had a shorter median time to achieve these endpoints (16 days (range 13–22) for Platelet20 and 19 days (range 16–42) for Platelet50)." (PMID 37206253, 2023). "Three patients (one with Hodgkin lymphoma and two with NHL) required more than four doses of plerixafor, but all eventually collected ≥2 × 106 CD34+ cells/kg." (PMID 22570654, 2012). "In one study of only Hodgkin lymphoma (HL) patients, CD34+MDSCs rather than M or G-MDSCs were identified at diagnosis and were found to be the only independent variable for reducing disease-free survival." (PMID 31640764, 2019).
squamous cell carcinoma (13 papers, 2003 to 2024). A carcinoma arising from squamous epithelial cells. "SOX2 expression is significantly higher in squamous cell carcinoma (SCC) CD34+ tumor initiating cells compared to CD34− cells." (PMID 38612911, 2024). "Sixty-five tumours (34 adenocarcinomas and 31 squamous cell carcinomas) showed vascular invasion, highlighted by CD34 immunostaining of endothelial cells." (PMID 12592367, 2003). "In the present study, we aimed to characterise whether the cell population with high CD34 and α6-integrin expression behave as cancer-initiating cells within ultraviolet-induced squamous cell carcinoma in mouse skin." (PMID 33123267, 2020). "For example, in an elegant study of squamous cell carcinomas, canonical Wnt signaling activation was shown to be critical in tumorigenesis of CD34+ bulge CSCs, and ablation of the β-catenin gene resulted in depletion of CD34+ CSCs and complete tumor regression in mice." (PMID 28356914, 2017). "CD34 expression, to differentiate the PTC from squamous cell carcinoma, also confirmed the diagnosis." (PMID 30408740, 2018). "We examined immunohistochemical expression of VEGF and PTEN and CD34 for microvessel density (MVD) in sections of formalin-fixed, paraffin embedded tissue blocks of 140 patients with squamous cell carcinoma of the larynx." (PMID 20546613, 2010). "Tumor vascularity using CD34 stained slides measured by Chalkley counting method as well as hypoxia-inducible factor (HIF)-1α and vascular endothelial growth factor (VEGF) immunoexpression was examined in 158 vulvar squamous cell carcinomas." (PMID 24165149, 2013). "In addition, repeated limit dilution transplantation tests of squamous cell carcinomas indicated that integrin α6β1-high populations generate additional cancers, while integrin α6β1-low populations cannot, regardless of whether the cells were CD34-low or CD34-high." (PMID 37444576, 2023).